HSPB1 (heat shock protein family B (small) member 1)
Diseases named in the same sentence as HSPB1 in open-access papers (continued):
Sharing a sentence is not in itself a finding about the gene and the disease.
cancer (136 papers, 2006 to 2026). A tumor composed of atypical neoplastic, often pleomorphic cells that invade other tissues. "Small heat shock proteins like HSPB1 are associated with multiple processes in cancer including invasion, control of apoptosis and drug resistance." (PMID 39165691, 2024). "On the one hand, HSPB1 overexpression is closely associated with poor outcomes in multiple human cancers as it promotes cancer cell proliferation and metastasis and inhibits cell death." (PMID 38041016, 2023). "HSPB1, a recently identified ferroptosis‐associated gene, has been proved to be involved in human diseases, including cancers." (PMID 37211949, 2023). "Overexpression of HSPB1 was associated with malignant properties of cancer cells, resistance to chemotherapy or radiotherapy, and poor prognosis." (PMID 35526007, 2022). "Low levels of HSP90AB1/TRAP1, HSPA6/TRAP1, and HSP90AA1/TRAP1 in urine increase the probability of the patient having cancer, whereas low levels of CCT2/HSP90AB1 and HSPB1*HSPA9 in urine are strongly associated with non-cancer groups." (PMID 34692733, 2021). "In the HSP20 family, HSPB6 was negatively associated with glycolysis in 14 cancers, while HSPB1 was positively associated with glycolysis in 11 cancers." (PMID 33225964, 2020). "In particular, the high expression of HSPB1 (HSP27) has been associated with poor prognosis in several carcinomas and osteosarcomas." (PMID 30060564, 2018). "Notably, HSPB1 has been the focus of considerable research within cancer studies, often linked to drug resistance and adverse prognosis." (PMID 39608715, 2024). "Furthermore, the HSPB1-encoded protein promotes cancer cell proliferation and metastasis, while protecting cancer cells from apoptosis." (PMID 34226298, 2021). "HSPB1 expression is associated with a variety of human cancers with poor clinical prognosis." (PMID 34226298, 2021). "Moreover, high levels of HspB1 expression affect tumor susceptibility to adjuvant cancer treatments, including chemotherapy, hyperthermia and radiation therapies." (PMID 24514166, 2014). "Besides, changes in HSPB1 expression are linked to tumor growth, metastatic potential, deleterious resistance to chemotherapy, tumor aggressiveness, and poor clinical outcomes in various types of carcinomas." (PMID 37501157, 2023). "For example, HSPB1 is positively associated with inflammation in basal but negatively associated with inflammation in luminal B. The definition of subtypes is significant and complicated across multiple cancer types, suggesting the necessity to consider subtype for tumor heterogeneity." (PMID 33225964, 2020). "HSPB1 encodes heat shock protein 27kD (HSP27), which was reported to affect various aspects of cancer progression." (PMID 41393507, 2025). "HSPB1 was reported to be overexpressed in many types of cancers, promoting tumorigenesis and resistance against many anticancer drugs and host immune responses." (PMID 40138733, 2025). "HSPB1 is an important molecular target that regulates many pathological processes in cancer, including drug resistance, apoptosis and metastasis." (PMID 41007338, 2025). "Among the 49 FRGs, HSPB1 was the only gene that was negatively correlated with ISCA1 in most cancer types." (PMID 39766805, 2024). "This increases the expression of stress survival proteins such as heat shock protein 27 (HSP27/HSPB1), an oncoprotein that responds to cancer cell insults, including chemotherapeutic stress, by antagonizing caspase activation and apoptosis." (PMID 39682146, 2024). "Other proteins, such as GADD45B and HSPB1, are known to be involved in stress response and cellular homeostasis, which are critical in tumorigenesis and cancer progression." (PMID 39763976, 2024). "Similar findings have been observed following paclitaxel treatment, another wildly-used anti-cancer drug, indicating the significant role of HSPB1 in chemotherapy-induced ferroptosis." (PMID 37454220, 2023).
cancer (continued). "For instance, HSPB1, one of the most studied members of sHSPs, has been found to be overexpressed and plays an important role in a variety of human cancers including breast, colon, liver and bladder." (PMID 36768927, 2023). "We investigated the correlation between HSPB1 expression and immune infiltration in cancers and predicted the target drug of HSPB1 using the TISIDB database." (PMID 37241117, 2023). "Heat shock protein beta-1 (HSPB1) is a crucial biomarker for pathological processes in various cancers." (PMID 37268925, 2023). "HSPB1 is a multifunctional protein that regulates cell differentiation and development, and inhibits apoptosis in cancer cells." (PMID 37241117, 2023). "To understand the correlation between HSPB1 expression and the immune system in pan-cancers, we conducted an analysis using the TISIDB website." (PMID 37241117, 2023). "Recently, HSPB1 is identified as a novel negative regulator of ferroptosis in several human cancer cells, such as Hela, U2OS, and LNCap cells." (PMID 37454220, 2023). "We noted that there was an adverse association between HSPB6 and HSPB1, where the expression of HSPB1 was elevated in most cancers and that of HSPB6 was decreased." (PMID 37241227, 2023). "The protein expression of HSPB1 in different cancer types was analysed in the Human Protein Atlas database." (PMID 37241117, 2023). "Consistently, HSPB1 knockdown led to opposite results, and treatment with Fer-1 attenuated the effect of erastin in HSPB1 knockdown cancer cells." (PMID 37454220, 2023). "To understand the expression of HSPB1 in other tumours, we performed a pan-cancer analysis of HSPB1 using the TIMER database and the TCGA database." (PMID 37241117, 2023). "To understand the relationship between HSPB1 expression and the immune system in pan-cancers, we performed an analysis using the TISIDB website." (PMID 37241117, 2023). "The combination of the antisense oligonucleotide Apatorsen of HSPB1 mRNA and a variety of anti‐cancer drugs enhances the effect of anti‐cancer drugs." (PMID 35152560, 2022). "BRD4 and HSPB1 have been found to upregulate ferritinophagy, and BRD4 and HSPB1 are highly expressed in many cancer types." (PMID 36339539, 2022). "The 12 FRGs are divided into 4 categories according to their functions: lipid metabolism (GPX4, LPCAT3, ACSL5, ACSL6), antioxidant (CD44, SESN2, AIFM2), iron metabolism (CISD1, HSPB1), and cancer metabolism (SOCS1, FH, G3BP1)." (PMID 35559049, 2022). "HSPB1 also increased cell proliferation by facilitating cell cycle progression, promoting migration and invasion, maintaining cancer stem cells, or inactivating the Hippo tumor suppressor pathway." (PMID 35526007, 2022). "HSPB1 has been identified as an essential mediator in cancer progression and preventing apoptosis in transformed cells." (PMID 35936690, 2022). "Consistent with previous reports on the relationship between HSP27 and metastasis [PMID: 23492367], cancer recurrences occurred more frequently in patients overexpressing HSPB1." (PMID 35931945, 2022). "Based on function, the 12 FRGs can be grouped into four classes: Lipid metabolism (GPX4, LPCAT3, ACSL5, and ACSL6), antioxidant metabolism (CD44, SESN2, and AIFM2), iron metabolism (CISD1 and HSPB1), and cancer metabolism (SOCS1, FH, and G3BP1)." (PMID 34784264, 2022). "HSPB1 is a key regulator of ferroptosis in cancer cells, and HSPB1 is a negative regulator of ferroptosis by reducing iron‐mediated production of lipid reactive oxygen species." (PMID 35152560, 2022). "We found that AS-tDR-007333 precipitated with several cancer-related RNA-binding proteins, including HSPB1, DHX9, ACTB, YBX3, and ILF2." (PMID 35526007, 2022). "A high expression of HSPB1 promotes proliferation and metastasis while protecting the cancer cells from apoptosis." (PMID 36437923, 2022).
cancer (continued). "Heat shock protein beta-1 (HSPB1) is a negative regulator of iron cancer cell death, and HSPB1, as a new regulator of iron cancer cell death in previous experiments, plays an important role in iron-mediated cancer therapy." (PMID 36531217, 2022). "Among the upregulated proteins, S100 family proteins, SFN, LDHA, and HSPB1 were all cancer-related proteins, which play important roles in tumor migration and invasion." (PMID 35936690, 2022). "HSPB1 is reported to be highly expressed in many cancers and participate in tumour cell proliferation." (PMID 34431214, 2021). "Of several HSPs including HSP70, HSP90, and HSP60, overexpression of small heat shock protein HSP27 (also known as HSPB1) is critical for cancer progression and metastasis and for the development of resistance to anticancer drugs." (PMID 33925114, 2021). "Concerning chemicals that target HspB1, only a few are currently tested for their efficiency and specificity, particularly in the cancer field where HspB1 is often considered as a crucial therapeutic target." (PMID 33923911, 2021). "Various basal levels of HspB1 constitutive expression have been observed in most human tissues and cellular types; an expression particularly intense in several cancer cells types." (PMID 33923911, 2021). "A similar conclusion can be drawn for different compounds targeting cancer cells where HspB1 has detrimental activity." (PMID 33923911, 2021). "There is also evidence that, in cancer cell models, HSPB1 is able to improve proteasome stability, allowing an increase in the complex ability to degrade proteins during ER stress by UPR." (PMID 34571827, 2021). "Here, we summarize the drugs aimed at reducing HspB1 expression or inhibiting its actions in cancer therapy." (PMID 32927696, 2020). "In this study, we identified this protein as supposedly differentially phosphorylated in the leiomyoma, suggesting a possible role of phosphorylated HSPB1 in promoting cell survival in cancer." (PMID 31100862, 2019). "HSP27/HspB1 is a potent cytoprotective chaperone, and it is overexpressed in many cancer types; thus, it is an attractive target in cancer therapy." (PMID 31533245, 2019). "Many of the functions of HSPB1 suggest important roles in several cancers including stomach, breast, ovary and prostate." (PMID 28903393, 2017). "Subpopulation B consisted of 121 cells (29.1%) and showed overexpression of 13 genes, including seven cancer genes (HSPB1, ANXA1, SLPI, KRT8, KRT19, KLK7, and ABL2) and several Keratin genes (KRT8, KRT7, KRT19, and KRT6B)." (PMID 28794488, 2017). "Heat shock protein 27 (HSP27, HSPB1) induces resistance to anticancer drugs in various cancer types, including non-small cell lung cancer (NSCLC)." (PMID 29285257, 2017). "It is known that HSPB1 expression increases dramatically upon hyperthermic insult and that reduction of HSPB1 activity with inhibitors will increase cancer cell sensitivity to a range of chemotherapies." (PMID 27626679, 2016). "Although increased blood serum HSPB1 levels have been observed in cancer patients, only a small number of studies have investigated the role of soluble HSPB1." (PMID 24465581, 2014). "HSPB1 is elevated in the serum of patients with many types of cancer, although its exact role in tumorigenesis and metastasis has yet to be determined." (PMID 24465581, 2014). "We have previously shown that overexpression of HSPB1 in cancer cells induces radio- and chemo-resistance." (PMID 24465581, 2014). "Serum HSPB1 has been suggested as a prognostic marker of tumor malignancy because HSPB1 serum levels are elevated in cancer patients." (PMID 24465581, 2014). "Here, we have reviewed the pro-oncogenic client proteins interacting with HspB1, HspB5 or HspB4 that can play crucial roles in human cancer pathologies." (PMID 24514166, 2014).
cancer (continued). "In cancer cells, active translation machinery is a prerequisite for cell growth and proliferation and once again HspB1 plays a major role in the protein translational initiation process." (PMID 24514166, 2014). "While RNAi strategies aimed at therapeutically decrease HspB1 level as well as the search for inhibiting drugs are nowdays deeply active, the use of HspB1 in the clinic is still mainly as a prognostic indicator of specific cancer types." (PMID 24514166, 2014). "Another worth noting point relates to HspB1 ability to enhance cancer cells resistance to a large panel of anti-cancer drugs." (PMID 24514166, 2014). "The literature is filled with reports describing the incredible number of roles played by small Hsps, particularly HspB1 and HspB5 in cancer cells." (PMID 24514166, 2014). "This pathway promotes cancer cell survival by up-regulating the survival kinase pAKT activity through its interaction with HspB1." (PMID 24514166, 2014). "This PKC region can sensitize human cancer cells by sequestring HspB1, hence inhibiting its interaction with pathological protein partners." (PMID 24514166, 2014). "HspB1, also known as heat shock protein 27, has been indicated to be a critical marker in several cancer cells." (PMID 23880933, 2013). "In that respect, HspB1 and HspB5 are essential for the growth of cancer cells and protect them against apoptotic or other types of death triggered by the immune system in the aim of their elimination." (PMID 24278676, 2012). "The problem exists because Hsps, and particularly HspB1 and HspB5, are often constitutively expressed, particularly in human cancer cells, where they counteract an apoptotic process decided by the cell." (PMID 24278676, 2012). "Amongst the many clients whose activity is modified by HspB1, one can cite the translation initiation factor 4E (eIF4E) which modulates the translational initiation process, a crucial parameter for cancer cell growth and proliferation." (PMID 24278676, 2012). "In that respect, the most studied protein has been HspB1 whose decreased level sensitized cancer cells to apoptotic inducers, anticancer drugs, and radiations and reduced their tumorigenic potential." (PMID 24278676, 2012). "Many cancer cells express high loads of Hsps, such as HspB1 and HspB5; a phenomenon which increases their resistance to numerous deleterious agents and conditions." (PMID 24278676, 2012). "Basal level cellular expression of inducible HSPB1 is upregulated in many cancer cells and confers a high level of resistance to radiation and chemotherapeutic agents in the absence of heat." (PMID 24213112, 2011). "Furthermore, NMIIA, S100A9, and HSPB1 upregulation in cancer has been correlated with the resistance of the targeted tumor to chemo‐, radio‐, and/or immunotherapy." (PMID 40138733, 2025). "HSPB1 is a protein from the small heat shock protein family with chaperone functions; its increased expression in some cancers promotes tumor progression and metastasis, and correlates with tumor chemoresistance and poor prognosis, although its role in the case of PAAD is controversial." (PMID 40141294, 2025). "However, mEHT upregulates heat shock protein beta 1 (HSPB1),a cancer-promoting stress chaperone molecule." (PMID 39144564, 2024). "The exact mechanism by which HSPB1 regulates cancer growth is still unknown; however, this small protein is involved in several tumours and takes part in several distinctive cancer features, including resistance to stress response and actin organization." (PMID 37569364, 2023). "Erastin enhances heat shock factor 1 (HSF1)-dependent HSPB1 expression in cancer cells." (PMID 38072908, 2023). "Interestingly, data reported in the literature indicate that the phosphorylation and dephosphorylation state of HSPB1 controls the apoptosis of cancer cells." (PMID 37569364, 2023). "Functional assays revealed that HSPB1 could promote cancer growth and metastasis in vitro and in vivo." (PMID 37454220, 2023).
cancer (continued). "The results showed that there was a correlation between HSPB1 expression and the abundance of tumour-infiltrating lymphocytes (TILs), immune activators, immunosuppressants, major histocompatibility complexes, chemokines and chemokine receptors in pan-cancers." (PMID 37241117, 2023). "HSPB1 was involved in the regulation of the immune system in most cancers." (PMID 37241117, 2023). "Many studies have investigated HSPB1 in relation to various cancer types." (PMID 37268925, 2023). "The increased expression of HSPB1 observed in late-stage malignancies suggests that HSPB1 may contribute to cancer development." (PMID 37268925, 2023). "HSPB1 has also been demonstrated to play a vital role in a wide variety of cancer." (PMID 37016377, 2023). "Additionally, HSPB1 and phosphorylated HSPB1 can reduce the iron uptake of cancer cells from the intracellular environment, thus maintaining iron homeostasis and reducing susceptibility to ferroptosis." (PMID 37723588, 2023). "The conditioned medium collected from HSPB1-overexpressing cells significantly promoted the migration of cancer cells and macrophages as well as the angiogenesis of HUVECs, which could be abrogated by the supplement of IL6 neutralizing antibodies." (PMID 37454220, 2023). "Previous studies reported that HSPB1 might be a negative regulator of ferroptosis, which was upregulated following erastin treatment in several cancer cells, such as Hela cells, U2OS and LNCap." (PMID 37454220, 2023). "In various cancer cell types, HSPB1, a heat shock protein, is highly induced by erastin therapy." (PMID 34784264, 2022). "HSPB1 acts as a negative regulator of ferroptosis in several types of cancer." (PMID 36570007, 2022). "Knockout of HSPB1 could enhance erastin-induced ferroptosis, but upregulation of HSPB1 could inhibit this effect in cancer cells." (PMID 35874632, 2022). "Moreover, suppression of HSPB1 phosphorylation and the heat shock factor-1- (HSF-1-) HSPB1 pathway can increase the anticancer effects of erastin in cancer cells." (PMID 35028002, 2022). "A study demonstrated that HSPB1 is a negative regulator of ferroptotic cancer cell death." (PMID 35559049, 2022). "HSPB1 is frequently upregulated in BC, wherein it promotes cancer cell growth and metastasis by inducing the SUMOylation of HSPB8 and increasing its expression, and SPINT1 was highly expressed in the HER2-positive type, with a relatively high rate in node-positive patients." (PMID 36428562, 2022). "Interestingly, it has been reported that HSPB1 correlates with the overall survival of patients with several types of cancer." (PMID 35204174, 2022). "In addition, heat shock protein beta-1 (HSPB1), a type of small heat shock protein, is found to be a negative regulator of ferroptotic cancer cell death." (PMID 34335189, 2021). "In addition, erastin has been reported to stimulate HSF1‐dependent HSPB1 expression in cancer cells to confer protection against ferroptosis." (PMID 33675143, 2021). "Overall, chemical downregulation of HspB1 is beneficial for some cancers." (PMID 33923911, 2021). "Furthermore, current reports indicate that HspB1 is associated with therapeutic resistance in colon, liver, and head and neck cancer cells through the regulation of ROS levels; thus, targeting sHSPs could be a potent strategy to help overcome chemo/radioresistance in cancers." (PMID 32927696, 2020). "Since HSPB1 is often overexpressed in cancers that developed resistance against cytotoxic drugs, these HSPB1 inhibitors could improve cancer chemotherapy as a cotreatment together with cytotoxic drugs." (PMID 32253739, 2020). "The reports are mainly focused on HspB1 as a molecular target for cancer therapy." (PMID 32927696, 2020).